EZH2 (enhancer of zeste 2 polycomb repressive complex 2 subunit)
Diseases named in the same sentence as EZH2 in open-access papers (continued):
Sharing a sentence is not in itself a finding about the gene and the disease.
ovarian tumors (continued). "The increased expression of EZH2 in ovarian tumors could explain the reported relative resistance of OC cells to EMT, or their preference towards MET, reverting to an epithelial phenotype immediately after dissemination from the primary tumor site." (PMID 27563817, 2016). "Furthermore, treatment of ovarian tumors with EZH2 and DNMT1 inhibitors increased the efficacy of tumor-associated antigen-specific CD8+ T cells in response to PD-L1 inhibition." (PMID 27199994, 2016). "In addition, using EZH2 inhibitors to specifically target ovarian tumors could ultimately improve patients outcomes." (PMID 37634008, 2023). "Inhibition of EZH2 activity using a clinically applicable small molecule inhibitor significantly suppresses the growth of CARM1-expressing, but not CARM1-deficient, ovarian tumors in two xenograft models and improves the survival of mice bearing CARM1-expressing ovarian tumors." (PMID 29434212, 2018). "Enhancer of zeste homolog 2 (EZH2)-mediated histone H3K27me3 and DNMT1-mediated DNA methylation suppress the ovarian tumor production of Th1-inducing chemokine, CXCL9 and 10, and decrease TIL in TME." (PMID 36991099, 2023). "MiR-506 targeted the EZH2 and Wnt/β-catenin signaling pathway to increase sensitivity toward PARP inhibitors and cisplatin in ovarian tumor cells." (PMID 37051101, 2023).
adenoma (22 papers, 2012 to 2025). A neoplasm arising from the epithelium. "Since then, additional whole-exome sequencing studies have corroborated low frequencies of EZH2 mutations in sporadic adenomas." (PMID 33269427, 2021). "When we compared EZH2 expression level with the tumor malignancy grade, type of carcinoma, and type of lesion (hyperplasia/adenoma/carcinoma) respectively, only carcinoma malignancy was found to have statistically significant association with EZH2 expression." (PMID 27502594, 2016). "For example, EZH2 mutation was observed in 1 of 8 adenoma exomes, and overall in 2/193 adenomas after direct sequencing of additional samples." (PMID 25594030, 2014). "Inhibition of EZH2 reduces adenoma progression and promotes immune activation in VCMsh2THu colorectal mucosa." (PMID 39946195, 2025). "IHC staining results further supported this trend, revealing low EZH2 protein expression in normal mucosa, moderate levels in adenomas, and higher expression in adenocarcinoma tissue, although these differences were not statistically significant." (PMID 39946195, 2025). "EZH2 is associated with carcinogen-induced transformation of HBEC and its depletion prevents progression from hyperplasia to adenoma in an NNK mouse model." (PMID 35924166, 2022). "Only DZNep treatment prevented progression of hyperplasia to adenomas in the NNK mouse lung tumor model through reducing EZH2 and affecting the expression of genes regulating cell growth and invasion." (PMID 33632299, 2021). "We continuously administered dox through the drinking water, leading to the depletion of Ezh2, followed by a significant impairment of the formation of adenomas compared with the GFPi controls." (PMID 30487290, 2018). "Consistent with the genetic ablation of Ezh2, we observed a dramatic decrease in the induction of mammary hyperplasias and early adenomas and a complete block in the formation of lung metastases in GSK-126-treated cohorts." (PMID 29959321, 2018). "In the present study, the EZH2 expression level in adenoma was similar to that in normal pancreatic duct, and it increased during IPMN progression." (PMID 25084021, 2014). "EZH2 expression displayed a similar pattern (normal duct<adenoma<borderline atypia<CIS ≈ invasive carcinoma) with cell proliferative activity." (PMID 25084021, 2014). "A small but growing literature has shown that EZH2 is expressed in pituitary adenoma cells in a manner that correlates with Ki-67 labeling but not in the normal pituitary gland, with likely roles in adenoma proliferation and possibly angiogenesis." (PMID 31040912, 2019). "EZH2 gene amplification at 7q36.1 locus is common in PCs (about 60% of cases), acting as an oncogene in parathyroid carcinogenesis and showing a significant over-expression of EZH2 mRNA and protein in malignant carcinomas compared with adenomas and hyperplastic parathyroid glands." (PMID 35282432, 2022). "Tissue samples of polyps or adenomas showed variable intensity of hypoglycosylated MUC1, phospho-p65 and EzH2 expression, from very low to moderately high." (PMID 29285251, 2017). "EZH2 expression in malignant (CIS and invasive carcinoma) IPMNs was significantly higher than that in adenoma and borderline-atypia IPMNs." (PMID 25084021, 2014). "Negative EZH2 expression (score 0) was frequently detected in sessile serrated adenomas/polyps (SSA/Ps) (76%) compared with hyperplastic polyps (HPs) (36%), traditional serrated adenomas (TSAs) (25%), and non-serrated adenomas (36%)." (PMID 26871294, 2016). "Our results illustrate a distinct overexpression of EZH2 in the tumors in comparison to normal AH tissue and a significant correlation of this overexpression with proliferation, irrespective of the adenoma subtype." (PMID 26593398, 2015).
adenoma (continued). "Fifty-four surgically resected pancreatic IPMN specimens, including a total of 181 lesions (normal duct in 48, adenoma in 50, borderline atypia in 53, carcinoma in situ (CIS) in 19, and invasive carcinoma in 11) were analyzed by immunohistochemical staining (EZH2, Ki-67, p27Kip1)." (PMID 25084021, 2014). "EZH2 highly correlates with proliferation rates, irrespective of the adenoma subtype." (PMID 26593398, 2015). "p27Kip1-positive cells were EZH2-negative in non-malignant IPMN (adenoma)." (PMID 25084021, 2014). "Interestingly, cell lines with high EZH2 protein levels have shown almost undetectable (HCT116) or low (SW620 and RKO) p-cofilin as compared to the other studied cell lines, with the exception of Caco-2 intermediate adenoma cell line." (PMID 25549357, 2014). "Regarding premalignant lesions, negative EZH2 expression was higher in SSA/Ps than in HPs, TSAs or non-serrated adenomas." (PMID 26871294, 2016).
endometriosis (21 papers, 2017 to 2025). The growth of functional endometrial tissue in anatomic sites outside the uterine body. "Increased enhancer of zeste homolog 2 (EZH2) expression in ESCs from endometriosis patients is linked to elevated m6A levels and repression of decidual genes like IGFBP1, suggesting crosstalk between m6A and histone modifications." (PMID 41568332, 2025). "Next, we calculated the diagnostic value of the 12 hub ATGs for endometriosis using the ROC analysis, and the results showed the high sensitivity and specificity of EZH2 (AUC: 99.0%) and RND3 (AUC: 94.0%) in diagnosing endometriosis." (PMID 34790699, 2021). "Changes in uterine EZH2 expression in women are also associated with endometrial hyperplasia, endometriosis, and uterine fibroids, suggesting that this enzyme is required for epigenetic programming in uterine epithelium and stroma." (PMID 33732505, 2020). "Targeting EZH2 may offer potential therapeutic strategies for managing inflammation and associated symptoms in endometriosis." (PMID 40630095, 2025). "Moreover, a recent study has reported that low expression of Pcdh10 is associated with high Enhancer of Zeste Homolog 2 (EZH2) expression and Histone H3 (H3K27me3) enrichment in the tissue of endometriosis patients." (PMID 37058252, 2023). "Consequently, there is a reason to believe that EZH2 plays important roles in the development of endometriosis through facilitating EMT, FMT and fibrogenesis, and causing epigenetic aberrations along the way." (PMID 28754964, 2017). "Hypoxia induces EZH2 expression in eutopic (endometriosis) ESCs, contributing to impaired decidualization." (PMID 40072055, 2025). "The experiment observed a significant increase in enhancer of zeste homolog 2 (EZH2) in the endometrium of patients with endometriosis." (PMID 40004233, 2025). "We investigated potential impact of EZH2 inhibitor GSK343 on endometriosis development in a mouse model." (PMID 40630095, 2025). "In mice, the EZH2 inhibitor GSK343 reduced TNFα levels and endometriosis progression, similar to gene knockdown of ERβ or EZH2." (PMID 40630095, 2025). "These epigenetic alterations show lesion-specific patterns, with deep infiltrating endometriosis (DIE) exhibiting higher levels of EZH2, H3K27me3, and H3K9me3 compared to ovarian endometriomas (OMA), suggesting progressive epigenetic reprogramming." (PMID 40072055, 2025). "This study explores how enhancer of zeste homolog 2 (EZH2) influences endometriosis, particularly through its interaction with estrogen receptors (ERs)." (PMID 40630095, 2025). "IGFBP1, a marker of decidualization induced by progesterone and cyclic adenosine monophosphate (cAMP), is downregulated in endometriosis due to overexpression of enhancer of zeste homolog 2 (EZH2)." (PMID 41009686, 2025). "EZH2 knockdown or inhibition has been tested in mice with induced endometriosis and prompted EZH2-induced epithelial-mesenchymal transition (EMT) in cancers." (PMID 36479105, 2022). "EZH2 can directly associate with EMT in downregulating E-cadherin expression by histone H3K27 trimethylation and indirectly through miR-361 suppressing endometriosis." (PMID 36316365, 2022). "Endometriosis is a known risk factor for the endometroid and clear cell subtypes of OC, and the peritoneal fluid from women with endometriosis has been shown to induce expression of EZH2 and H3K27me3 in OC cell lines." (PMID 35326450, 2022). "This work has shown EZH2 and RND3 to have a high value in diagnosing endometriosis and being effective diagnostic biomarkers." (PMID 34790699, 2021). "The expression of EZH2 was obviously higher in eutopic and ectopic endometrium in the endometriosis group compared with the control group." (PMID 34790699, 2021). "This suggests that EZH2 in endo PF treated cells is having more of an effect on the expression of all genes in the array (PRC2 complex core, alternate and binding partners) when compared to JARID2 further supporting a role for EZH2 in endometriosis." (PMID 33800594, 2021).
endometriosis (continued). "ChIP-qPCR was used to better understand the regulatory roles of JARID2 and EZH2 and their cross-interactions in endometriosis." (PMID 33800594, 2021). "This opens the door for testing newer targets in addition to the EZH2 inhibitors and miRNA mimics/antagonists currently being tested in endometriosis." (PMID 33800594, 2021). "A role for EZH2 in promoting trophoblast EMT is consistent with its known role in promoting this process in endometriosis." (PMID 33732505, 2020). "miR-200b-3p was associated with the transcription factors DNMT1, EZH2, HNF1B, JUN, MYB, ZEB1, and ZEB2 during the pathogenesis of endometriosis." (PMID 32802844, 2020). "One potential candidate that is suspected to be involved in epigenetic and post-translational modifications and EMT program in endometriosis is Enhancer of Zeste homolog 2 (EZH2), which was reported to be upregulated in endometriosis." (PMID 28754964, 2017). "In summary, the expression of EZH2 and its associated PRC2 proteins, along with H3K9me3 and H3K27me3, are elevated in endometriosis." (PMID 28754964, 2017). "In this study, we found that the expression of EZH2 and its associated PRC2 proteins, along with H3K9me3 and H3K27me3, are elevated in endometriosis." (PMID 28754964, 2017). "Here, we show that EZH2 expression, along with its associated PRC2 proteins, is significantly elevated in ectopic and eutopic endometrium from women with endometriosis as compared with control endometrium." (PMID 28754964, 2017). "In view of the seemingly concomitantly elevated expression of PRC2 constituents and of H3K27me3 and H3K9me3, we conclude that EZH2 is very likely to be functional in the development of endometriosis." (PMID 28754964, 2017). "This suggests that EZH2 may be involved in nociceptive sensitization in endometriosis by exacerbating the inflammatory response." (PMID 40004233, 2025). "Additionally, our human study demonstrated increased EZH2 expression in endometriotic lesions, accompanied by upregulation of ERβ and TNFα, as well as suppression of ERα, indicating that EZH2 plays a significant role in endometriosis development." (PMID 40630095, 2025). "We assessed the mRNA levels of EZH2, ERα, ERβ, and TNFα in endometriosis lesions." (PMID 40630095, 2025). "We developed a schematic model for EZH2-mediated endometriosis progression." (PMID 40630095, 2025). "We recently showed the PF can modulate the EZH2/H3k27me3 axis in endometriosis." (PMID 34900746, 2021). "This provides strong indication that EZH2 may be a potential therapeutic target for the treatment of endometriosis." (PMID 28754964, 2017). "Taken together, EZH2/PRC2 may play a central role in the regulation of EMT process in endometriosis." (PMID 28754964, 2017). "It is tempting to propose that EZH2-targeting agents may be useful for endometriosis patients harboring high levels of EZH2." (PMID 28754964, 2017). "Thus, EZH2 promotes TNFα-driven inflammation, contributing to endometriosis." (PMID 40630095, 2025). "Additionally, EZH2 was identified as a novel driver of EMT in endometriosis." (PMID 34820775, 2022). "Besides its crucial role in EMT induction, EZH2 may also influence development of endometriosis via other mechanisms." (PMID 28754964, 2017). "Conversely, the EZH2 inhibitor GSK343 reduces EZH2-driven H3K27me3 modifications, thereby suppressing TNFα levels and impeding endometriosis development." (PMID 40630095, 2025). "We investigated the in vivo effects of the EZH2 inhibitor GSK343 on inflammation and redox balance in peripheral blood within an endometriosis mouse model." (PMID 40630095, 2025). "The EZH2 inhibitor GSK343 was shown to suppress TNFα expression and endometriosis development in a mouse model." (PMID 40630095, 2025). "Based on their findings, miR-200b-3p was linked to transcription factors such as DNA methyltransferase 1 (DNMT1), enhancer of zeste homolog 2 (EZH2), Hepatocyte nuclear factor-1-beta (HNF1B), MYB, JUN, ZEB1, and ZEB2 during endometriosis pathogenesis." (PMID 36289820, 2022).
endometriosis (continued). "Among them, the differences in the expression levels of EZH2, IQCG, and RND3 between the endometriosis group and control group were the most statistically significant (p < 0.001)." (PMID 34790699, 2021). "In view of above results, protein expression of EZH2, RND3, and IQCG were subsequently measured in endometriosis cells and tissues by Western blotting, which demonstrated similar results to those of the mRNA level." (PMID 34790699, 2021). "We showed that when PF from women with endometriosis was added to endometrial cells, there was an increase in the PRC2 complex, specifically EZH2, and its target H3K27me3." (PMID 34900746, 2021). "Spearman correlation analysis depicted that the relative expression levels of EZH2 and RND3 were positively correlated with CA125 of the corresponding endometriosis samples, (r = 0.7817, p < 0.0001) and (r = 0.7793, p < 0.0001), respectively." (PMID 34790699, 2021). "Activation of trimethylation of histone 3 lysine 27 (H3K27me3) by EZH2, a component of the Polycomb repressive complex 2 (PRC2), is suggested to play a role in endometriosis." (PMID 33800594, 2021). "When compared to the EuN tissues, expression of all three PRC2 protein complex (SUZ12, EED and EZH2) and JARID2, was higher in both the eutopic (EuE) and ectopic (EcE) tissue from endometriosis patients." (PMID 33800594, 2021). "The expression levels of EZH2 (Enhancer of Zeste homolog 2) and RND3 (also known as RhoE) had statistically significant changes with higher values in the endometriosis group compared with the controls, both in the tissue samples and primary ESCs." (PMID 34790699, 2021). "Then, DNMT1, EZH2, HNF1B, JUN, MYB, ZEB1, and ZEB2 were found as TFs related to endometriosis by interacting with target genes of miR-200b-3p." (PMID 32802844, 2020). "Thus, EZH2/PRC2 may serve as an important mediator of TGF-β1-induced EMT in endometriosis." (PMID 28754964, 2017). "Second, we have provided both in vitro and in vivo evidence to show that inhibition of EZH2 can abolish EMT, thus disrupting the progression of endometriosis development." (PMID 28754964, 2017). "Treatment with an EZH2 inhibitor results in suppression of lesion growth and reduced EMT and fibrosis in mouse with induced endometriosis." (PMID 28754964, 2017). "Treatment with an EZH2 inhibitor results in suppression of lesion growth, improved generalized hyperalgesia, and reduced EMT and fibrosis in mouse with induced endometriosis." (PMID 28754964, 2017). "However, whether EZH2 regulates EMT in endometriosis is unclear." (PMID 28754964, 2017). "Targeting EZH2, as with GSK343, could be a promising therapeutic strategy for endometriosis treatment." (PMID 40630095, 2025). "Silencing EZH2 by siRNA reduced H3K27me3 enrichment and increased PCDH10 expression, resulting in decreased invasion and migration of endometrial stromal cells and providing a target for the treatment of endometriosis patients." (PMID 37058252, 2023). "qPCR was used to determine the mRNA expression of PRC2 components SUZ12, EED, and EZH2 in eutopic tissue from women with no endometriosis (EuN, n = 5) or women with endometriosis (EuE, n = 10) and ectopic tissue from women with endometriosis (EcE, n = 6)." (PMID 33800594, 2021). "At present, there are many related studies on the role of EZH2 and SIRT1 in endometriosis." (PMID 34790699, 2021). "The top 5 genes were the following: EGFR, EZH2, VEGFA, JUN, and FN1 with a degree >15; thus, they might be regulated by miR-200b-3p and play important roles in the progression of endometriosis." (PMID 32802844, 2020). "To test this hypothesis, we conducted a mouse study to see whether EZH2 inhibition using DZNep can suppress EMT and subsequent FMT and fibrogenesis in mice with induced endometriosis." (PMID 28754964, 2017). "Since activated platelets induce EZH2 expression, it is possible that platelet-induced EMT and fibrogenesis in endometriosis may be mediated, at least in part, by EZH2 and its associated PRC2." (PMID 28754964, 2017).
endometriosis (continued). "By showing that EZH2 induces EMT and platelets activates EZH2 expression in endometriotic epithelial cells, this study essentially demonstrates the importance of epigenetic regulation in EMT in endometriosis." (PMID 28754964, 2017). "In vivo administration of 3-Deazaneplanocin A (DZNep), an EZH2 inhibitor, significantly inhibited the growth of endometriotic lesions and improved generalized hyperalgesia, along with attenuated EMT and reduced fibrosis in endometriosis." (PMID 28754964, 2017). "Here, we investigated whether EZH2 induces EMT in endometriosis, and whether the specific inhibition of EZH2 could reverse the EMT phenotype, suppress migratory ability of endometriotic cells and retard the growth of endometriosis in vivo." (PMID 28754964, 2017). "DZNep also significantly abrogated the expression of EZH2, EED, SUZ12, H3K9me3 and H3K27me3 in eutopic/control endometrial epithelial cells from mice with or without induced endometriosis, all in a dose-dependent manner." (PMID 28754964, 2017). "Here, using eutopic and ectopic tissues, as well as peritoneal fluid (PF) from IRB-approved and consented patients with and without endometriosis, the expression of PRC2 complex components, JARID2, miR-155 (known regulators of EZH2), and a key inflammatory modulator, FOXP3, was measured." (PMID 33800594, 2021).